ENSG00000212206
Synonyms: LOC124900396
Gene: Small nucleolar RNA gene on chromosome 17 (8,329,583 to 8,329,719, forward strand). Ensembl gene ENSG00000212206.
Gene Ontology:
Biological process: RNA processing
Cellular component: nucleolus
Homologues: Orthologues: rat LOC120099449 (68% identical), rat Snora69 (67% identical), mouse Gm22784 (65% identical). Paralogues in human: SNORA69 (84% identical).